CRP (C-reactive protein)
Diseases named in the same sentence as CRP in open-access papers (continued):
Sharing a sentence is not in itself a finding about the gene and the disease.
Stroke (continued). "Following stroke, increased auto-immune activity is a common response, and it has been shown that up-regulated inflammation markers like C-reactive protein (CRP), as a consequence of a prolonged auto-immune response, relate to poor prognosis." (PMID 27176617, 2016). "While GGT showed a positive association with stroke risk in the model adjusted for traditional risk factors including CRP, the association with coronary heart disease (CHD) risk was abrogated when CRP was included in their model." (PMID 27195017, 2016). "Longitudinal studies in stroke indicated that CRP levels can be persistently elevated over several months after stroke." (PMID 26599129, 2015). "Elevated levels of CRP have been described from 3 h after stroke onset, with a plasmatic peak between 36 and 48 h, and an ability to predict outcome lasting several days." (PMID 26543408, 2015). "Elevation of serum CRP has been found to be a good predictor of various CV outcomes, such as myocardial infarction and stroke in the general population and in individuals undergoing dialysis." (PMID 26474473, 2015). "Markers of inflammation and innate immune responses, including C-reactive protein (CRP), IL-6, TNF-α, and several cell adhesion molecules, are linked to the occurrence of myocardial infarction and stroke among patients with coronary heart disease." (PMID 26693381, 2015). "After the acute event of stroke, concentrations of the pro-inflammatory cytokine IL-6 and the acute phase protein CRP in brain tissue and peripheral blood are increased since they are rapidly released by activated cells." (PMID 25613713, 2015). "During the third day following stroke onset, two well-known proteins of the inflammatory pathway—CRP and IL-6—were found to be indicators of prognosis in our population." (PMID 26543408, 2015). "IL-10 and CRP at 6 h, as well as NIHSS on admission, were identified as independent predictors of stroke-associated infection." (PMID 25613713, 2015). "They concluded that tryptophan metabolism strictly correlated with the stroke-related inflammatory response measured by C-reactive protein, erythrocyte sedimentation rate and NLR." (PMID 25205210, 2015). "Therefore, this longitudinal study was to explore associations between serum CRP levels and fatigue during the first year follow-up after stroke, and to explore whether CRP levels at one month predict fatigue at a later stage after stroke." (PMID 26599129, 2015). "This is the first study to investigate the relationship between CRP and fatigue over time after stroke." (PMID 26599129, 2015). "Inflammation is an important pathophysiological response to stroke, which is characterised by the changed levels of peripheral inflammatory biomarkers, including C-reactive protein (CRP)." (PMID 26599129, 2015). "CRP, an acute phase protein considered a marker of systemic inflammation, has been shown to be an independent predictor of stroke, myocardial infarction, atherosclerosis, peripheral vascular disease and sudden cardiac death." (PMID 26703686, 2015). "Recently, the predictive ability of both, IL-6 and CRP within 3 days after stroke for post-stroke infection has been reported." (PMID 25613713, 2015). "For example, CRP and glycohemoglobin were jointly associated with CHF and stroke, whereas triglycerides and glycohemoglobin were jointly associated with angina." (PMID 25788869, 2015). "Participants with more health behaviors were younger, of male gender, had a higher PIR, lower cotinine level, less likely to have emphysema, chronic bronchitis, and stroke, and had lower CRP levels." (PMID 26106588, 2015). "Based on these studies, we conducted this community based, prospective study to explore the relationship between CRP concentrations and the incidence of stroke and its subtypes in Chinese." (PMID 25191699, 2014). "The age- and sex-standardized incidence per 1000 person-years of stroke subtypes according to hs-CRP concentrations." (PMID 25191699, 2014).
Stroke (continued). "Whilst CRP had the highest sensitivity (83.7%), cardiac TnI was the most specific (97.3%) for prediction of poor stroke outcome (cut-off: >0.09μg/L)." (PMID 25184809, 2014). "Whilst CRP had the highest sensitivity (83.7%), cardiac TnI was the most specific (97.3%) for prediction of unfavourable short-term stroke outcome, with cut-off value of >0.09μg/L." (PMID 25184809, 2014). "In a previous study by our group cardioembolic stroke appears as the “less atherosclerotic” among each diagnostic subtype of stroke, reporting the correlation of PWV only with CRP and vWF." (PMID 24571954, 2014). "The elevation of serum CRP is considered an independent risk factor for atherosclerosis, particularly in women, besides predisposing to acute myocardial infarction (AMI), cerebrovascular accident (stroke), peripheral artery disease and sudden death." (PMID 25329057, 2014). "A larger study subsequently found an association between CRP and all-cause mortality, in addition to a composite endpoint of TIA/stroke, systemic embolism, acute coronary syndrome, acute heart failure, and cardiac death." (PMID 25215263, 2014). "Hazard ratios (HR) and 95% confidence intervals (95% CI) of all stroke and stroke subtypes according to serum hs-CRP concentrations." (PMID 25191699, 2014). "We thus investigated the relationship between CRP and the risks of all stroke and its subtypes in a Chinese adult population." (PMID 25191699, 2014). "In ischaemic stroke patients, IV IL-1Ra reduces peripheral inflammation (plasma IL-6, white cell count, and C-reactive protein, CRP) measured 7 days after stroke." (PMID 24383930, 2014). "We therefore conducted a large prospective study to investigate the relationship between CRP concentrations and stroke and its subtypes, i.e. ischemic stroke (IS), hemorrhagic stroke (ICH) and subarachnoid heamorrhage (SAH) using samples from Kailuan Study." (PMID 25191699, 2014). "C-reactive protein (CRP), as a biomarker of inflammation, is involved in stroke and cognitive impairments, and KO phospholipids demonstrated anti-inflammatory responses, lowering CRP levels in human subjects." (PMID 23351783, 2013). "C-reactive protein also rises with vascular insufficiency and damage of most types, which includes acute myocardial injury or infarction, stroke, and peripheral vascular compromise." (PMID 23484158, 2013). "The clinical importance of possible relation between CRP and functional outcome of stroke is unclear." (PMID 24353532, 2013). "Several studies have shown that C-reactive protein (CRP), an inflammatory marker, is associated with stroke severity and outcome." (PMID 23514014, 2013). "Alternative approaches, such as meta-analysis or studies including greater cohorts of patients, are necessary to clarify the relation between CRP levels and different stroke etiologies." (PMID 24527683, 2013). "CRP, IL-6, white blood cells (WBCs), mean body temperature and National Institutes of Health Stroke Scale (NIHSS) score were measured at the time of admission." (PMID 23935729, 2013). "Terruzzi and collaborators showed higher plasma levels of CRP in CE stroke patients when compared with other TOAST subtypes within the first 6 hours after symptoms onset." (PMID 24527683, 2013). "Extensive studies demonstrated that the peripheral levels of white blood cell (WBC), homocysteine (HCY), and C-reactive protein strongly correlate with stroke severity and independently predict mortality and stroke recurrence in acute ischemic stroke patients." (PMID 24023414, 2013). "Overall, our study identified dynamic alterations of serum YKL-40 levels following AIS and demonstrated that YKL-40 measurement is superior to that of CRP for discerning AIS patients from stroke-free elderly controls." (PMID 23272150, 2012). "CRP, a sensitive indicator of systemic inflammation, has been shown to be powerful indicator of stroke severity and functional outcome of AIS." (PMID 23272150, 2012).
Stroke (continued). "This association remained significant even after adjustment for age, sex, smoking, alcohol consumption, frequency of exercise, self-reported past history of stroke, waist circumference, and CRP (both as a continuous variable), with significant P for trends." (PMID 22685652, 2012). "Angiotensin-converting enzyme (ACE) inhibitors can lower median CRP levels and result in better long-term outcome in stroke patients, after controlling for confounding variables and concomitant treatments." (PMID 21356305, 2011). "C-reactive protein is a biomarker of inflammation and its increase level predicts cardiovascular events such as stroke, coronary heart disease, or peripheral vascular disease." (PMID 20885777, 2010). "S100B has previously been found to be correlated with CRP in subjects with acute ischaemic stoke at 12, 24 and 72 hours after stroke, after controlling for gender, age and leukocyte count." (PMID 21034449, 2010). "Data on mortality from vascular events only, would have been more ideal as this would directly link the role of CRP in stroke outcome." (PMID 19400931, 2009). "The high CRP group had a higher frequency of stroke of cardioembolic origin (38% in the high CRP group vs. 21% in the low CRP group)." (PMID 19400931, 2009). "A few previous studies were done in which CRP was measured early after stroke onset (within 12 hours)." (PMID 19400931, 2009). "The survival was poorer in the high CRP group not only immediately after stroke, but also for our observation period of 2.5 years." (PMID 19400931, 2009). "Previous studies show that C-reactive protein (CRP), an inflammatory marker, is associated with stroke outcomes and future vascular events." (PMID 19400931, 2009). "We studied the effect of CRP measured within 24 hours after stroke onset on functional outcome, mortality and future vascular events." (PMID 19400931, 2009). "A small number of papers with a relatively small number of patients have studied the time course of CRP after stroke onset." (PMID 19400931, 2009). "Various prospective studies have found initial CRP levels to be higher in persons who develop stroke, ischemic heart disease, and peripheral artery disease." (PMID 17597836, 2007). "While C-reactive protein (CRP) and white blood cell (WBC) count are individual risk markers, the predictive value of a combined inflammatory score (IS) for stroke prevalence remains unclear." (PMID 42195341, 2026). "In the context of the clinical presentation, exclusion of common stroke mechanisms, and a favorable response to corticosteroids, both clinically and para-clinically with a marked decline in CRP, the findings were considered most consistent with possible immune-related cerebral vasculitis." (PMID 41988182, 2026). "Additionally, Tongxinluo significantly improved NIHSS, total cholesterol (TC), and serum hypersensitive C-reactive protein (hs-CRP) levels in stroke individuals." (PMID 40761406, 2025). "A markedly elevated CRP may also prompt clinicians to consider more aggressive secondary prevention or to closely monitor for post-stroke complications such as infection." (PMID 40869247, 2025). "The univariate logistic regression analysis presented that stroke history, NIHSS score on admission, MOCA score, lymphocytes, fibrinogen, D-dimer, total cholesterol, low-density-lipoprotein, eGFR, hs-CRP, and SUA/SCr are all associated with early-onset PSCI (all p < 0.05)." (PMID 40671786, 2025). "Targeting CRP with anti-inflammatory treatments may improve outcomes or prevent stroke recurrence, although the effectiveness of such treatments in reducing post-AIS risk remains unclear." (PMID 39910895, 2025). "This threshold may be a limitation, and future research should incorporate sensitivity analysis to refine it in conjunction with CRP blood levels in stroke patients." (PMID 39910895, 2025). "Stroke patients have elevated levels of CRP, FPG, HbA1c, TG, and NPAR." (PMID 39935611, 2025).
Stroke (continued). "Additionally, stroke patients exhibited elevated CRP levels, diminished self‐care abilities, and reduced physical activity (lower total metabolic equivalent of task (MET))." (PMID 40791098, 2025). "Despite this, they did find a correlation between CRP and stroke severity." (PMID 40447994, 2025). "Advanced models incorporating C-reactive protein, D-dimer levels, and hypoxia markers could enhance the prediction of secondary complications such as post-stroke edema, hemorrhagic transformation, or delayed neurological deterioration." (PMID 40283502, 2025). "Elevated CRP levels in patients with more severe disability emphasize the contribution of systemic inflammation and oxidative stress to stroke severity, as CRP can activate NADPH oxidase, enhance ROS production, and impair endothelial nitric oxide signaling, thereby amplifying neuroinflammation." (PMID 41300462, 2025). "Logistic regression analyses showed that younger age, female, higher National Institute of Health Stroke Scale score, higher interleukin-6 level, and higher hypersensitive C-reactive protein level were major predictive factors for the moderate and high symptom groups." (PMID 40709232, 2025). "As such, CRP remains an accessible, cost-effective, and integrative biomarker in stroke care." (PMID 40869247, 2025). "The primary outcome was MACE and secondary outcomes included all-cause and cardiovascular mortality, non-fatal MI, stroke, revascularization, heart failure, CRP/hs-CRP changes, and adverse effects." (PMID 41517355, 2025). "Immunological and inflammatory biomarkers, including IL-1β, IL-6, TNF-α, IL-10, IL-8, IL-17, and CRP, have become indispensable tools in stroke research, offering insight into how the immune system shapes both the extent of brain injury and the trajectory of recovery." (PMID 40869247, 2025). "Additionally, these inflammatory mediators can raise C-reactive protein (CRP) levels, which has been connected to a higher risk of stroke." (PMID 40491586, 2025). "Therefore, increased CRP levels have been correlated with more pronounced depressive symptoms shortly after stroke, but their impact appeared to diminish over time." (PMID 40943152, 2025). "Previous studies, including our own analysis on ICU-admitted cerebrovascular patients, have shown that inflammatory markers such as high-sensitivity C-reactive protein (hs-CRP) and the neutrophil-to-lymphocyte ratio (NLR) are associated with adverse outcomes in stroke patients." (PMID 40371080, 2025). "Stroke can trigger the production of inflammatory markers such as C-reactive protein (CRP), interleukin-6 (IL-6), and tumor necrosis factor-alpha (TNF-α), which stimulate osteoclastogenesis and inhibit osteoblast function, leading to accelerated bone resorption and osteoporosis." (PMID 39792154, 2025). "On the other hand, this finding may imply a direct influence of CRP on specific T cell populations in stroke." (PMID 40342517, 2025). "Together with elevated CRP levels, this profile reflects not only systemic inflammation but also an altered oxidative balance, reinforcing the concept of oxidative stress as a key determinant of stroke severity and recovery." (PMID 41300462, 2025). "This suggests that inflammation may play a more prominent role in clot formation in cardioembolic strokes, reinforcing earlier findings on serum CRP and further supporting its utility as a biomarker for stroke etiology." (PMID 41227149, 2025). "Additionally, sex differences in inflammatory markers such as IL-6, CRP, and S100B were observed, with these biomarkers being more elevated in female stroke patients." (PMID 40356948, 2025). "Median CRP values ranged from 2.8 mg/L in the first 24 h to 7.0 mg/L on 120-144 h after stroke." (PMID 40447994, 2025). "Additional investigation into CRP could enhance our understanding of thrombo-inflammation in strokes of different etiologies." (PMID 39910895, 2025).
Stroke (continued). "When performing a subgroup analysis according to stroke etiology, we also did not observe any association between high CRP level and any of the outcomes." (PMID 40682467, 2025). "Similarly, CRP mediated the stroke–possible sarcopenia and stroke–severe sarcopenia relationships, with higher CRP levels accounting for 7.1% and 16.8% of the total effects, respectively." (PMID 40791098, 2025). "High-sensitivity CRP (hs-CRP), although nonspecific, continues to be a reliable predictor of stroke risk and recurrence." (PMID 40949500, 2025). "Evaluating these characteristics may improve the prognosis for GCA‐related strokes and decrease diagnostic delays by promptly informing clinicians of the stroke site, ECU results, and CRP levels." (PMID 39817601, 2025). "The relationship between CRP and stroke outcomes can be attributed to a two‐step mechanism." (PMID 40353608, 2025). "Moreover, stroke survivors with cognitive impairment exhibit increased inflammation, with C-reactive protein, IL-6, and TNF-α serving as predictors of PSCI." (PMID 39911922, 2025). "Cardiovascular risk factors, including glycated hemoglobin (5.4 vs. 5.2, p < 0.001), systolic blood pressure (136.5 vs. 128.2 mmHg, p < 0.001), and C-reactive protein (3.5 vs. 2.5, p < 0.001), were significantly higher in the stroke group, while HDL cholesterol was lower (48.2 vs. 51.6, p < 0.001)." (PMID 40726629, 2025). "A modest elevation in WBC may be seen in a few patients the first 24 h after stroke, and in body temperature and CRP the following 24 h." (PMID 40447994, 2025). "Second, inflammatory markers such as C-reactive protein and procalcitonin were not included, hindering the ability to explore the relationship between these markers, malnutrition, and stroke-associated pneumonia." (PMID 40144568, 2025). "Furthermore, mediation analyses were performed to evaluate the potential mediation effects of CRP on the associations of METS-IR and UA with the risk of stroke." (PMID 39634177, 2024). "Univariate logistic regression analysis showed significant differences in age (OR 1.044, 95% CI 1.017–1.072, p = 0.001), previous stroke (OR 3.289, 95% CI 1.296–8.344, p = 0.012), CRP (OR 0.990, 95% CI 0.986–0.995, p < 0.001), albumin (OR 1.559, 95% CI 1.017–2.390, p = 0.042)." (PMID 39734631, 2024). "Among AIS patients, our study examined whether stroke recurrence mediated the relationship between LDH or hs-CRP levels and functional outcomes at 90 days, with exploring the extent of this mediation effect." (PMID 39280700, 2024). "Additionally, stroke survivors with increased circulating interleukin (IL)-1β and c-reactive protein (CRP) have higher levels of post-stroke fatigue." (PMID 38802847, 2024). "First, we only assessed baseline hs-CRP levels in the acute phase of stroke." (PMID 37848651, 2024). "Finally, we performed a mediation analysis using CRP as a mediator, providing an explanatory perspective on the relationship between METS-IR and uric acid (UA) levels and stroke risk." (PMID 39634177, 2024). "Moreover, plasma CRP, Hcy, and NE counts exhibited significant positive correlations with stroke severity and poor functional outcomes, including NIHSS before and after treatment, mRS after treatment, mRS at 90 days, and mRS at 1 year." (PMID 39238889, 2024). "Additionally, the levels of serum IL-6 and CRP in stroke patients after CEA were 3.08 ± 0.78 pg/mL and 3.09 ± 1.38 ng/mL respectively, which were significantly higher than those in the control group (1.02 ± 0.27 pg/mL, 1.64 ± 0.6 ng/mL, respectively)." (PMID 37611898, 2024). "Therefore, we included possible confounders that can affect BT, such as stroke subtypes, neurological severity, CRP as an inflammatory factor, and acute infectious complications in this study." (PMID 38206979, 2024). "Moreover, higher CRP levels have been demonstrated to independently predict survival after ischemic stroke and functional outcomes following thrombolytic stroke." (PMID 38895632, 2024).